IL1B (interleukin 1 beta)
Diseases named in the same sentence as IL1B in open-access papers (continued):
Sharing a sentence is not in itself a finding about the gene and the disease.
metabolic disorders (continued). "As the most important component of bacterial endotoxin, LPS has been shown to aggravate metabolic disorders by elevating IL-1β, TNF-α, and IL-6 expression, which might be related to TLRs." (PMID 35774596, 2022). "Moreover, chronic inflammation (as assessed by different biomarkers such as proinflammatory adipokine, leptin, and/or proinflammatory cytokines IL-6 and IL-1β) has been described to play a crucial role in the development of metabolic disease." (PMID 36006128, 2022). "In concurrence with metabolic dysfunctions, overfeeding has been well accepted to trigger an inflammatory response, and the release of inflammatory factors such as TNF-α, IL-1β, CRP, and soluble adhesion molecules have also been causally linked to metabolic disorders." (PMID 35126096, 2021). "In particular, IL‐1β is an important mediator of inflammasome‐related metabolic diseases." (PMID 33377656, 2020). "In fact, pro‐inflammatory genes as TNF‐ɑ, IL‐1ɑ, IL‐1β, and NLRP3 are associated with a wide range of age‐related disorders, including cardiovascular, neurodegenerative, and metabolic diseases and the level of soluble TNF‐ɑ R1 was identified as a predictor of 10‐year all‐causes of mortality." (PMID 30488553, 2019). "This indicates that caspase-1 may have a profound effect on lipid metabolism through IL-1β and IL-18 pathways, suggesting that it might play a significant role in adipose tissue as well as in metabolic diseases." (PMID 28153032, 2017). "In this study, whether there are different expressions of IL-1β, IL-18, and IL-22, which had been reported to be involved in metabolic disorder and insulin sensitivity, is interesting but yet investigated." (PMID 26681840, 2015). "GM dysbiosis and inflammation also induce epigenetic alterations in cytokine genes, such as IL-1β, IL-6, TNF-α, NF-kB, BTLA, IL-18R1, TGF-β, P13k/Akt1, Ctnnb1, and Hsp90aa1, as well as DNMTs, HDACs, and DAT1 associated with the development and progression of metabolic disorders and/or NPDs." (PMID 41228440, 2025). "Moreover, activation of IL-1β in AD is linked to the NLRP3 inflammasome, and we have reported NLRP3 inflammasome formation and IL-1β activation in visceral adipose tissue and pancreas, known intermediaries of metabolic diseases." (PMID 33626069, 2021). "Therefore, NLRP3-dependent pyroptosis and maturation of pro-inflammatory effectors (IL-1β/IL-18) induced by ROS could contribute to development of autoimmune and even metabolic diseases, such as DCM." (PMID 28790925, 2017). "IL1β, IL6, and TNFα are cytokines that are well identified as the inflammation markers involved in the metabolic disease of fish." (PMID 38671834, 2024). "It has been reported to play an important role in autoimmune and metabolic diseases by activation of CASP1 and production of IL-1β and IL-18." (PMID 36694200, 2023). "When activated, NLRP3 inflammasome triggers the release of pro-inflammatory interleukins (IL)-1β and IL-18, an essential step in innate immune response; however, defective checkpoints in inflammasome activation may lead to autoimmune, autoinflammatory, and metabolic disorders." (PMID 33435142, 2021). "Vast pharmacological efforts have been invested in developing treatments for metabolic diseases by focusing on pro-inflammatory cytokines as TNF-α, IL-1β, and IL-61,2,33,34." (PMID 30996248, 2019). "However (4.3.2), during metabolic disorders caused by excess energy, the NLRP3 inflammasome is likely to be activated by aberrant lipid metabolites and/or high glucose levels, which subsequently results in the secretion of IL-18 as well as IL-1β, which can induce inflammatory responses." (PMID 30717382, 2019). "During the development of metabolic disorder, adipose tissue is considered to be a major source of inflammatory mediators, such as TNF-α, IL-1β, IL-6 and IL-17, which negatively affect adipocyte function." (PMID 30709353, 2019).
metabolic disorders (continued). "There is a clear association between the inflammatory biomarkers used to calculate the DII score (CRP, IL-1β, IL-6, TNF-α, IL-4, and IL-10) and cardio-metabolic diseases such as obesity, diabetes, or CVD." (PMID 27527152, 2016). "This is in agreement with previous findings that neutrophil elastase KO mice have reduced levels of IL-1β in the liver and serum and that diminished NLRP3 inflammasome and caspase-1 activity elicits protection from high-fat diet mediated metabolic disorder." (PMID 26405763, 2015). "some studies suggest that pro-inflammatory cytokines IL-1β and TNF-α suppress the expression of CYP7A1 and NTCP, leading to decreased BA synthesis and a reduction in the hepatic-enterohepatic circulation rate, thereby contributing to BA metabolic disorders." (PMID 41255527, 2025). "Inhibition of proinflammatory cytokines TNFa, IL1β, or MCP1 reverses metabolic disorders." (PMID 37734559, 2023). "Interestingly, saturated fatty acids were found to induce the release of pro-inflammatory cytokines, such as IL-6, IL-1β and TNF-α, from immune cells into blood circulation, particularly in individuals with metabolic disorders." (PMID 34681074, 2021). "Hence, this endocrine disruptor may be responsible for the development of metabolic disorders, promoting in fat cells an increase in proinflammatory pathways and upregulating the expression and release of certain cytokines, such as IL6, IL1β, and TNFα." (PMID 37175934, 2023). "Additionally, IL-1β and TNF-α levels are chronically raised in metabolic disease." (PMID 36005503, 2022). "This forms the basis why new drug candidates, such as natural polyphenols, which prevent IL-1β secretion by inhibiting the function of NLRP3 or other inflammasome components, have lately been under scrutiny in relation to immunological, neurological, and metabolic diseases." (PMID 34062977, 2021).
neurological diseases (97 papers, 2009 to 2026). "High expression of IL1B within the central nervous system (CNS) is believed to induce neuronal damage, which is associated with numerous neurological disorders, such as PD." (PMID 41601963, 2026). "Maternal intrauterine infection associated with increased levels of pro-inflammatory cytokines (IL-6, TNF-α, IL-1β) is the most important cause of preterm birth and neonatal neurological disorders." (PMID 35155393, 2022). "Microglia expressing iNOS are found in many neurological diseases, and multiple stimuli such as LPS, IL-1β, TNF-α, and IFN-γ can cause the expression of iNOS, which synthesizes NO to directly damage neuronal cells." (PMID 34122094, 2021). "In patients with end-stage neurological disease, chronic activation of astrocytes by IL-1β caused downregulation of TIMP-1 mRNA and protein expression in CSF and brain tissues." (PMID 30062663, 2019). "BBB disruption is a common pathological feature of various neurological diseases, and inflammatory cytokines such as IL-1β and TNF-α have been considered as causative factors that damage BBB integrity by downregulating TJ proteins in BBB endothelial cells." (PMID 25535736, 2014). "Wnt5a was also involved in Human Immunodeficiency Virus (HIV) associated neurological disorders by promoting IL-1β, IL-6 and TNF-α production in the spinal cord." (PMID 24993819, 2014). "Additionally, the ERS-related proteins were downregulated following anti-TNF-α and anti-IL-1β treatment, including those implicated in neurological disorders such as HYOU1, PDIA4, and PDIA3." (PMID 40338234, 2025). "COX-2, increased IL-10 and TGF-β1 in the brain tissue of rats and reduced plasma cytokines TNF-α, IL-1β, IL-2, IL-3, IL-4, IL-5, IL-6, etc. and exotoxin activity in plasma of different neurological disorders." (PMID 40297338, 2025). "Il-1β can be synthesized by various cell types in the CNS, depending on models of neurological disorders." (PMID 37443034, 2023). "The pro-inflammatory cytokines tumor necrosis factor alpha (TNFα) and interleukin-1beta (IL-1β) play a crucial role in the homeostasis of the central nervous system (CNS), a number of neurological diseases, and CNS injury and repair." (PMID 35625761, 2022). "Many studies have revealed that systemic inflammation-induced neurological disorders are mediated by proinflammatory cytokines, such as interleukin-1β (IL-1β), through multiple dissociable mechanisms, such as neuronal dysfunction and neuronal death." (PMID 35831435, 2022). "During CM Plasmodium parasites sequestered in the CNS within erythrocytes cause the production of proinflammatory cytokines, such as TNF-α, LTα, IFN-γ, IL-1α, and IL-1β, which contribute to the hyperinflammatory state of this neurological disorder." (PMID 35222377, 2022). "The analyzed cytokines Il1b, Il6, Tnfa, and Tgfb all play important roles in various neurological disorders and have multiple functions involving cell differentiation, growth, and survival." (PMID 32833183, 2021). "Pyroptosis involves the release of intracellular proinflammatory factors (including IL-18 and IL-1β), and pyroptosis-regulated cell death plays a key role in the pathogenesis of various neurological diseases including SCI." (PMID 34764819, 2021). "Stem cell therapies for nervous system disorders have revealed promising results on targeting and downregulating the proinflammatory factors such as IL-1β, TNF-α, and IFN-γ." (PMID 34671255, 2021). "Inflammation, which was mimicked by treating neural cells with IL-1β, a cytokine elevated in multiple neurological diseases, triggered specific changes in CD8+ T cells." (PMID 33968073, 2021). "The TLRs activated their downstream pathways and then induced NF-κB and Pro-Il-1β, both of which are related to neuroinflammation and the pathogenesis of a variety of neurological diseases." (PMID 34093653, 2021). "The over-production of IL-1β, IL-6, and TNF-α cytokines is a hallmark of neurological diseases in the brain." (PMID 31835609, 2019).
neurological diseases (continued). "Investigation of NLRP3’s role in several neurological disorders reveals that excessive inflammatory signature observed in these pathologies is most often due to increased IL-1β levels in the brain and cerebrospinal fluid of patients." (PMID 31892810, 2019). "Interleukin-1β (IL-1β), a key cytokine that drives neuroinflammation in the Central Nervous System (CNS), is enhanced in many neurological diseases/disorders." (PMID 30044427, 2018). "Considering the crucial role of microglial inflammasome/caspase-1/IL-1β axis in neuroinflammation, we propose that the inhibition of DAPK1 represents a potential therapeutic application for IL-1β-associated neurological diseases." (PMID 29967321, 2018). "High levels of pro-inflammatory cytokines such as TNF-α, IL-6, and IL-1β were found elevated in the brain tissue from patients with neurological diseases." (PMID 29719536, 2018). "In summary, although the mechanisms behind the effect of IL-1β on cortical perfusion and neural activity remain to be determined, our findings have important implications for the many neurological disorders in which IL-1β is known to have a key role." (PMID 27557843, 2016). "In line with this, elevated brain protein levels of TNF-α, IL-1β, and IL-6 have been reported in rodent mTBI models as well as within human CSF within hours of injury, as they have in other neurological disorders." (PMID 25879458, 2015). "A growing body of evidence indicated that IL-1β expression is one of the earliest and most important neuropathological factors in numerous diseases of the nervous system, including AD." (PMID 25585621, 2015). "IL-1β is considered to be a critical factor for astrocyte activation in various neurologic disorders." (PMID 25313834, 2014). "Interleukin-1β (IL-1β) is a pro-inflammatory cytokine that is involved in the pathogenesis of a number of neurological disorders, possibly as a modulator of glutamatergic response." (PMID 21314939, 2011). "Recent studies highlight the P2X7/NLRP3/IL-1β pathway in neurological diseases." (PMID 40732240, 2025). "In fact, some studies indicate that different regulatory mechanisms control IL-1β and IL-18 secretion, which is an important consideration in understanding their effects in several neurological disorders, including HD." (PMID 33776778, 2021). "Therefore, a balance in IL-1β and IL-1ra productivity in the brain is intimately involved in the pathogenesis of neurological diseases." (PMID 24621600, 2014). "Levels of ACh and pro-inflammatory cytokines IL1-β and IL-17 were measured both in cerebrospinal fluid (CSF) and sera of 22 RR-MS patients in the relapsing phase and in 17 control subjects affected by other non-neurological diseases (OND)." (PMID 23202919, 2012). "It was demonstrated that SAA might play an important role in the pathogenesis of neurological disorders by up‐regulating the expression of the cytokine interleukin‐1β (IL‐1β), which is mediated by the Nod‐like receptor protein 3 (NLRP3) inflammasome, cathepsin B, and caspase‐1." (PMID 34018701, 2021). "In these neurological disorders, pro-inflammatory markers such as TNF-α, IL-1β, IL-2, INFγ, NOS, and ROS are increased according to postmortem brain samples." (PMID 38516464, 2024). "Recent work has shown that blocking pro-inflammatory cytokines, including TNFα, IL-1β, and IL-6, can reduce the permeability of BBB and improve the outcomes of neurological diseases and injuries to a great extent." (PMID 36353359, 2022). "IL-1β is known to be a negative regulator of NSC proliferation in hippocampal neurogenesis and restoration in many neurological disorders." (PMID 35178162, 2022). "However, in some conditions, studies have found that cytokines such as TNFα, IL-1β, and IL-6 can also improve the outcome of diseases such as ADs and that neutralizing or knocking out these cytokines can eventually attenuate the progression of neurological diseases or injuries." (PMID 36353359, 2022).
neurological diseases (continued). "IL-1β disrupts BBB in two ways: First, IL-1β can activate ACs to disrupt BBB and exacerbate the progression of the neurological diseases or injuries." (PMID 36353359, 2022). "Various neuroinflammatory and neurological diseases are characterized by a relative increase in M1 microglia-related factors such as TNF-α and IL-1β." (PMID 34604212, 2021). "Of all secreted cytokines, both in experimental and clinical conditions, tumor necrosis factor alpha (TNF-α) together with interleukin 1 beta (IL-1β) and interleukin 6 (IL-6) dominate in the pathogenesis of SCI and other neurological diseases." (PMID 32801994, 2020). "Given the evidence for P2X7Rs involvement in CNS neurological disorders and expression of SAA in AD and MS brain, the findings presented here propose a link between P2X7R, SAA, and IL-1β in CNS pathophysiology." (PMID 29803222, 2018). "Thus, administering PEFPs reduced IL-6, TNF-α, and IL-1β in hippocampal cells, inhibited the TNF-α and reduced NF-kB in the brain in different neurological disease models." (PMID 40297338, 2025). "Additionally, their correlation analysis indicated positive correlations between serum miR-128 levels and serum IL-1β and the TNF-α levels in neurological disorder patients." (PMID 38541185, 2024). "In addition to major cytokines, such as TNFα, IL-1β, IL-6, and their receptors, other cytokines also play an important role in neuroinflammation and neurodegeneration and may provide some promising new targets for clinical application to treat neurological disease and injury." (PMID 36353359, 2022). "We started our characterization of IL-1β in MS by examining well-characterized paraffin-embedded tissue blocks of five donors without neurological disease and of 17 MS patients." (PMID 27266875, 2016). "Our findings reveal novel mechanisms of BBB disruption by IL-1β, and suggest that SHH could be used therapeutically against various neurologic diseases." (PMID 25313834, 2014). "Furthermore, the expression and predominance of inflammasome components and the participation of IL-1β in neuropathogenesis was confirmed using an in vivo model of lentivirus (FIV)-induced immunodeficiency and neurological disease." (PMID 24886384, 2014). "Upregulated NLRP3 expression may enhance caspase-1-mediated inflammatory cascades and further stimulate the production of downstream inflammatory molecules, including IL-1β, IL-6, and TNF-α, all of which lead to an inflammatory response in a variety of neurological diseases." (PMID 36364939, 2022). "Although none of the patients with inactive disease showed neurologic disorder, their counterparts showed higher mean levels of serum TNF-α and IL-1β (41.50 ± 33.98 pg/mL and 20.53 ± 16.00 pg/mL, resp)." (PMID 25548434, 2014). "Compared to an HIV-1 positive patient without neurological disorder, HAND patients have increased levels of IL-8, the production of which is probably induced by IL-1β and TNF-α through MAPK pathways." (PMID 22727020, 2012).